CD4 (CD4 molecule)
Diseases named in the same sentence as CD4 in open-access papers (continued):
Sharing a sentence is not in itself a finding about the gene and the disease.
infection (continued). "In CD4-negative somatic cells, free viral particle entry has been reported in vitro but was overall inefficient, and viral internalization by vesicular uptake was essentially a dead end with respect to productive infection (46, 52, –, 59)." (PMID 32999017, 2020). "However, Lm-specific CD4 T cells can provide sufficient protection to infection even in the absence of CD8 T cells." (PMID 32903436, 2020). "What is not known is whether existing peripheral CD4 T cells are sufficient to control infection or whether a continuous supply of new T cells is important for controlling bacterial infection." (PMID 32722409, 2020). "Exhaustion is accompanied by increased expression of inhibitory receptors that dampen immune responses, and CD4 T cells from septic hosts have greater expression of inhibitory receptors including PD-1, 2B4, BTLA, and TRAIL, which directly impacts their ability to effectively respond to infection." (PMID 32733454, 2020). "Interestingly, we observed that anti-CD20 injection previous to infection affected neither the frequency and number of total CD4+ T cells nor T-bet expression in CD4+ T cells." (PMID 32398312, 2020). "It has been suggested that DCs directly facilitate HIV-1 transmission by either becoming infected, internalising virus via Dendritic Cell-Specific Intercellular adhesion molecule-3-Grabbing Non-integrin (DC-SIGN) for trans-infection of CD4 T cells and/or modulating IR to HIV-1." (PMID 31978062, 2020). "Moreover, the percentage of brain CD4+ and CD8+ T cells producing IFN-γ, an essential cytokine in ECM pathogenesis, was significantly decreased upon P. berghei K173 infection compared to that with P. berghei ANKA." (PMID 32265335, 2020). "Consequently, CCR5 has been recognized as a key drug target against HIV, and here we discovered that infection of whole-blood samples with MVA downregulates cell surface expression of CCR5 in DCs, CD4+ T cells, CD8+ T cells, and B cells of HIV-1-infected patients." (PMID 33013882, 2020). "However, in the early stage of the infection and in the absence of CD4 T cells, CD8 T cells and NK cells secrete IFNγ and are able to control the bacterial load." (PMID 33042146, 2020). "Rather, the increased number of effector T cells correlated with increased expression of CD25 on the surface of effector CD4+ and CD8+ T cells in the brain, which is consistent with previously published results examining the effects of ICOS blockade only in the chronic phase of infection." (PMID 31978191, 2020). "Our work provides valuable insight into the mouse model of infection and emphasizes how critical CD4+ T cells are for clearance, and further work is necessary to determine whether or not this translates to human infection." (PMID 32184237, 2020). "Moreover, autologous CD4+ T cells transduced with a lentiviral vector expressing an antisense targeting HIV env were infused to 13 ART-treated patients followed by treatment interruption, attempting to block viral replication upon infection." (PMID 32775304, 2020). "P10 is responsible for inducing lymphoproliferation and contains a major CD4+ specific T cell epitope and elicits an IFN-γ-dependent Th1 immune response, which is considered a protective and effective immune response against the infection with fungi of the genus Paracoccidioides." (PMID 32722452, 2020). "These opposing effects may be why Vpr does not have a clear positive or negative impact on infection of cycling CD4+ T cells in vitro." (PMID 32726944, 2020). "Although the frequency of CMV specific CD4+ T cell memory responses are expanded compared to those established at the time of infection, there is very little evidence of continual accumulation, so called “memory inflation,” of CMV specific CD4+ T cells over time in humans." (PMID 32509591, 2020).
infection (continued). "As expected, a substantial proportion of TFH cells (ICOS+Bcl6+) formed by 7.5 days post infection (~30% of CD4+ T cells) while only few follicular regulatory T cells (TFR, Foxp3+Bcl6+) were generated by this time point, representing ~7% of Foxp3+ T cells and ~0.5-1% of all CD4+ T cells." (PMID 33519801, 2020). "CD4+ and CD8+ T cells that specifically react to membrane proteins of the bacteria decline in infected humans from 1 year after infection, which is different from the long-lasting T cell response in C57BL/6 mice, and it was suggested that this may be due to a lack of memory response." (PMID 33091016, 2020). "Therefore, the evolution of the CD4+/CD8+ ratio showed no significant variation throughout the experimental infection." (PMID 32054530, 2020). "Taken together, these results suggest that CD103+CD4+TRM subset (Th1 and Th17) are distinct from CD103− CD4+TRM subset (Th1) and might play a different role in the mucosa following oral vaccination and/or infection." (PMID 32098623, 2020). "Thus, the expression of IL-10 by CD4+ T cells upon primary infection with S. aureus is likely one of the factors contributing to the lack of robust long-lasting protective CD4+ T cell memory responses." (PMID 33291260, 2020). "In addition, it was observed a decrease in the frequency of Th1-like memory CD4+ Treg in HCPS, important to highlight that this signature could be preserved even years after resolution of infection." (PMID 32984065, 2020). "Accordingly, we suggest that the CRD of galectin-3 monomers interact with HIV-1 gp120 or CD4 molecules, triggering galectin-3 oligomers formation to further enhance their binding capabilities to CD4 or gp120, respectively, thus facilitating HIV-1 CRF07_BC infection." (PMID 32485969, 2020). "Although we reported a difference in the frequency of TB-specific IFN-γ+CD38+ and IFN-γ+HLA-DR+ CD4+ T cells in the TB/HCV group, we did not observe an association between the frequency of these cells and the outcome of infection or response to anti-TB therapy." (PMID 31952232, 2020). "This leads to enhanced differentiation of naïve T-helper cells into effector T-helper/Memory cells [CD3+CD4+CD8α+CD8β-CD27-], which are capable of secreting high amounts of effector cytokines leading to efficient clearance of heterologous challenge virus at the site of infection." (PMID 33391267, 2020). "This would allow us to discern whether or not the observed increase in Salmonella-specific CD4+ T cells measured in thymectomized mice was a function of thymectomy alone, or a response to infection." (PMID 32722409, 2020). "Studies testing the efficacy of a variety of subunit vaccines have indicated that both CD4+ and CD8+ T cells are vital for providing protection from infective and intracellular T. cruzi; however, little is known about the phenotype of the T cells that must be activated to control Tc infection." (PMID 33414785, 2020). "Evidence suggests that the predominant presence of HTLV-1 in CD4+ T-cells rather than CD8+ T cells might be a post-infection event due to selective clonal expansion over time." (PMID 33414779, 2020). "It is plausible that the observed perturbances in CD4+ T cell and B cell phenotypes may have resulted from the increased STI infection that accompanied multivariant infection, which may then normalize upon STI treatment which was provided for all symptomatic participants." (PMID 32886726, 2020). "However, the levels of CCR5+CD4+ T cells did not undergo any significant alterations in the axillary LNs or the jejunum at any point during the course of infection." (PMID 32119719, 2020). "In addition, absence of Tregs in the priming stage of infection skewed CD4+ T cells towards a Th2 phenotype." (PMID 32423043, 2020). "Furthermore, in vitro infection of PBMCs but not CD4+ T cells of healthy donors carrying the MAVS minor genotype resulted in decreased levels of viral replication." (PMID 32708557, 2020).
infection (continued). "Overall, IFN-γ–producing CD4+ T cells remained present in the spleen of WT and Icos-/- mice at day 35 p.c., as the maintenance in IFN-γ production may contribute to the control of the relapsing infection after re-challenge." (PMID 32348365, 2020). "For a more detailed study of the role and function of CD8+ (and CD4+ T cells) in protection against R. typhi, 2 animal models have been developed in recent years: immunodeficient C57BL/6 RAG1-/- and BALB/c CB17 SCID mice, both of which lack adaptive immunity but behave differently in the infection." (PMID 33091016, 2020). "CD4+ TRM cells share many cardinal features of CD8+ TRM cells—they populate barrier sites and mucosal organs (e.g., lung, skin, salivary glands, intestine), they mediate local protection against infection, they phenotypically express CD69 and CD11a and share a core transcriptional signature." (PMID 32858901, 2020). "Here we found that infection of whole blood of HIV-ART patients with MVA significantly downregulated CCR5 in B cells (p = 0.001), HLA-DRbright DCs (p = 0.012), HLA-DRhigh DCs (p = 0.016), pDCs (p = 0.008), CD4+ T cells (p = 0.008), and CD8+ T cells (p = 0.008)." (PMID 33013882, 2020). "Both WKV and S2 peptides proved capable of evoking CD4 and CD8 T cell proliferative responses in cats experimentally infected with FIPV-i3c2, and implemented a valuable tool for a longitudinal investigation of antiviral T cell responses during primary and rechallenge infections." (PMID 31118053, 2019). "Moreover, EBOV virions bind to resistant Jurkat and activated CD4+ T-cells in a TIM-1 dependent-manner without productive infection." (PMID 30893855, 2019). "This disagreement with the literature could be explained by the fact that CD4 T cell responses are primed very late during infection and peak at d21–28 p.i., when IRF-5 is not strongly expressed by myeloid cells." (PMID 32038622, 2019). "Similarly, production of ZIKV-specific IgM was disrupted in the absence of CD4+ T cells mainly after IVag but not RO infection." (PMID 30677097, 2019). "Infection of target cells with unmodified infectious virus will downregulate CD4 from the cell surface, supporting presentation of “native trimer” envelope conformations, as opposed to CD4-induced (CD4i) monomeric conformational states." (PMID 31134085, 2019). "Flow cytometry was used to measure the peripheral lymphocyte subsets including CD3+T cells, CD4+T cells, CD8+T cells, CD19+B cells, CD3-CD16+CD56NK cells, and CD3+CD16+CD56NKT cells in 25 healthy controls and 52 treatment-naive SLE patients, among whom 13 were complicated with infections." (PMID 30994732, 2019). "In the present study we therefore measured production of IFN-γ by antigen-stimulated spleen cells and the frequency of CD4+IFN-γ+ and CD8+IFN-γ+ splenocytes of each mouse group after stimulation with PMA and ionomycin, as a measure of commitment to cytokine production during infection." (PMID 31475014, 2019). "Simultaneous infection of DCs with Chlamydia and HIV might be beneficial for the host as this triggers a higher HIV-specific CTL activation and lower transfer of HIV to autologous CD4+ T cells." (PMID 31178863, 2019). "De novo virus can subsequently be transferred to CD4+ T cells across the virological synapse, which uses adhesion factors such as intercellular adhesion molecular 1 (ICAM-1) to stabilize DC-T cell contacts, with infection being established more effectively than direct infection by free virus." (PMID 31156637, 2019). "However, recent studies that employed indirect techniques to infer the sites of HIV-1 entry into CD4+ T cells have concluded that endocytosis does not contribute to infection." (PMID 30691001, 2019). "Interestingly, while HIV-1 Vpr was found to be crucial for the infection of macrophages, it did not facilitate the infection of non-dividing CD4+ T cells." (PMID 31652959, 2019).
infection (continued). "Strikingly, the frequencies of circulating regulatory CD4+ T-cells remain unchanged in EBOV, hantaviruses and severe DENV infections, which may account for the massive T-cell activation, chronic inflammation, and disease severity observed in these infections." (PMID 30678246, 2019). "The frequency of CD4 T cells did not change at 2 weeks post-infection independently of mouse genetic background, while the frequency of CD8 T cells was already lower in deficient genotypes compared to WT both before and after infection." (PMID 30923339, 2019). "Thus, CD4+ T cells could be important mediators of protection against ZIKV, depending on the infection or vaccination context." (PMID 30677097, 2019). "Further, we detected an increased proliferative activity in CD4+/CD8+ T cells (constituting of cytotoxic and memory cells) and cytotoxic (CD8+) subtypes of αβ T cells, which was pronounced after first infection with a lesser increase after second infection resembling a memory response." (PMID 31539406, 2019). "The CAR contained CD4 extracellular and transmembrane domain, which might have increased CAR T cell susceptibility to infection, but lacked costimulatory domains, which could limit cellular functionality." (PMID 31552045, 2019). "However, after 24 hours of infection, the number of cells without PICs was 1.7-fold higher in CD4+ T cells from patients with LGMD1F than in healthy controls (p<0.001)." (PMID 31465518, 2019). "We demonstrate that while the endogenous NP311-specific CD4 T cell response is largely IFNγ-focused, with cells presumably belonging to the Th1 subset, NP311-specific CD4 T cells represent only a small fraction of the total antigen-experienced CD4 T cells in the lungs following infection." (PMID 31632414, 2019). "Therefore, to observe if the infection could prime the production of IFN-γ, we evaluated the production of IFN-γ by CD4+ and CD8+ T cells in infected and naive mice." (PMID 31192210, 2019). "Nevertheless, MHC-II down-modulation is more pronounced in the moment of infection in which adaptive immunity begins to be relevant, i.e., when IFN-γ secreted by T lymphocytes is stimulating the presentation of Brucella antigens to MHC-II-restricted CD4+ T cells." (PMID 31572389, 2019). "In addition, irrespective of the route of infection, HIV causes a rapid and profound depletion of CD4 T cells in the gut3." (PMID 30778066, 2019). "However, no synergistic effect was observed for the combination of anti-CD35 antibody and rCCL-5: rCCL-5 at a lower concentration (1 nM) despite the previous report did not inhibit HIV trans-infection from RBCs of CD4+ T cells (data not shown)." (PMID 31772057, 2019). "Additionally, experiments using LysMCre+Ifnar1fl/fl and Ifnar1−/− mice show that CD4+ T cells also play a role in Ab production during secondary infection but are not required to protect against systemic lethal challenge." (PMID 30677097, 2019). "However, our data indicate that unlike RBCs, these chemokine receptors do not play an important role in HIV trans-infection by CECs of uninfected CD4+ T cells in vitro." (PMID 31772057, 2019). "This implies that in the absence of CXCR6 expression, CD4+ T-lymphocytes may be recruited to the lungs earlier or potentially undergo a greater degree of proliferation at the site of infection." (PMID 30899256, 2019). "This increase in the IFN-γ+ CD4 and CD8 T-cell proportion suggests that IRT may enhance relative T-cell function acting in the pro-inflammatory cell-mediated Th1 response, making SAD patients better able to respond to infection through IRT immunomodulation." (PMID 31613907, 2019). "We then employed a virus-free approach to confirm that the mechanism of selective use of certain primate CD4 receptors stems from weak CD4 binding, as opposed to other interactions between HIV-1 and CD4 that may occur during the course of an infection." (PMID 31181085, 2019).
infection (continued). "Furthermore, cytokine (IFN-γ and IL-10) production during infection was also attributed to CD4+ but not CD8+ T cells." (PMID 31824512, 2019). "The Th2 CD4+ T cells expressing IL-4 and Treg cells expressing CD4+CD25+Foxp3+ and CD4+CD25–Foxp3+ were significantly induced at the early intestinal stage (6 days post-infection, day 6) and NBL migration stage (day 15) compared to the those of uninfected mice." (PMID 31703440, 2019). "Reduced infection of CD4+ T-lymphocytes with R5 but not X4 HIV-1 may restrict initial viral replication or slow the rate at which HIV-1 switches its co-receptor phenotype." (PMID 31487324, 2019). "Also, the impact of competition among CD4 T cell responses that likely occurs during complex immune responses, such as that induced by infection and vaccination is not yet well-understood, particularly during sequential, periodic confrontations." (PMID 31134060, 2019). "In addition, our findings suggest that specimens with LAg-pending and BRAI-invalid test results with both high CD4+ T cell counts and HIV-1 VLs may truly be recent infections." (PMID 31125356, 2019). "We found that in HIV-infected untreated subjects with moderate immune-suppression, CD4+ cells expressing CCR6 and CD161 were depleted, possibly reflecting their permissiveness to infection and redistribution from the blood to the GI tract in progressive infection." (PMID 30763359, 2019). "These immunologic signatures are derived from stimulation or perturbation of CD4+ and CD8+ T-cells by over-expressing T-REG markers and/or elaboration of cytokines, reduction of certain cytokine-activated proteins and/or T-cell immune environment activation upon infection." (PMID 31797958, 2019). "Lastly, we previously demonstrated that exposure of CD4+ T cells to EBOV resulted in the induction of both a pro-apoptotic and pro-inflammatory response, which is consistent with the reported effects of HIV abortive infection ultimately attributed to cell death." (PMID 31648236, 2019). "The proportion of exhausted CD4 T cells with this pseudo-Tfh phenotype increases over time during chronic LCMV infection, and the targeted deletion of these cells compromises the late arising, high affinity, neutralizing anti-viral antibody response which aids containment of the infection." (PMID 30781904, 2019). "Importantly, as antibody production and immunoglobulin class switch are CD4+ T helper cell-dependent, these results imply that sufficient help was provided only when CD4+ T cells were primed by OVA sensitization under conditions of concomitant infection." (PMID 30845208, 2019). "In agreement with the gene array data, PleC CD4+ T cells did not produce IL-21 during the active Th2 phase of infection (d 20 pi), but did produce IL-21 protein at d 60 pi, during the hypo-responsive phase of infection." (PMID 31815932, 2019). "However, CD4+ T cell depletion decreased production of IL-2 and IL-10 in early stage infection, decreased production of IL-17 and TNF-α, and abolished IL-3 production in both early and late stage infection." (PMID 31608052, 2019). "We observed an increased frequency of CD4+ iNKT cells in patients who did not develop infection." (PMID 31253189, 2019). "Interestingly, CD4+ T cells did not seem to have an impact on antibody neutralization of the virus measured by infection of C6/36 cells." (PMID 30761131, 2019). "However, prior DENV immunity had no impact on either the transcriptional profile of the CD8 T cells, nor the capacity of CD4 or CD8 T cells to produce IFN-γ at later stages of infection." (PMID 31382545, 2019). "Thus, CD4+ T cells do not appear to play an essential role in protecting against lethal primary or secondary infection with ZIKV." (PMID 30677097, 2019).